IL33 (interleukin 33)
Diseases named in the same sentence as IL33 in open-access papers (continued):
Sharing a sentence is not in itself a finding about the gene and the disease.
tumor (continued). "Treatment with chemotherapeutics and ICIs adversely promotes IL33+ tumor growth and metastasis through the release of IL33, which systemically expands immunoregulatory ST2+ cells in mouse tumor models, as with the unexpected hyperprogression that is sometimes seen in ICI-treated patients." (PMID 33535613, 2021). "Despite the absence of direct experimental evidence, a potential involvement of IL-33 in ICD contributing to the control of tumor growth could be inferred from the activation of the NLR family pyrin domain containing 3 (NLRP3) in dendritic cells (DCs)." (PMID 34209038, 2021). "IL33 also greatly contributes to angiogenesis through the recruitment and activation of not only immunosuppressive ST2+ MDSCs that produce VEGF, FGF, and MMP9 but also inflammatory ST2+ cells, including tumor-associated macrophages (TAM) and mast cells." (PMID 33535613, 2021). "It was suggested that IL-33 may also indirectly promote proliferation, the transformation of tumor cells, and metastasis through cooperation with oncogenes." (PMID 34209038, 2021). "Moreover, the administration of exogenous IL-33 to ST2-proficient tumor-bearing mice reduced activation and cytotoxic activity of NK cells, promoting tumor growth." (PMID 34209038, 2021). "In addition, IL-33 enhances transforming growth factor β (TGF-β) release from macrophages, derives the invasive and drug-resistant properties and further upregulating IL-33 expression of tumor cells." (PMID 34895039, 2021). "Indeed, the presence of cytokines, such as IL-12 together with IL-33, promote type 1 anti-tumor immune responses." (PMID 34209038, 2021). "Thus, IL‐33 secretion in the tumour sites induced M2‐like macrophage differentiation and favoured tumour growth and tumour metastasis in ESCC." (PMID 33305406, 2021). "Therefore, we can envisage a feed-forward loop where cancer cells stimulate in macrophages the production of GPNMB that binding to the CD44 receptor on tumor cells triggers the release of IL-33." (PMID 34583655, 2021). "Similarly, transgenic expression of IL-33 significantly increased the activation, proliferation, and cytotoxicity of NK cells due to enhanced NF-κB signaling and promoted their tumor infiltration in vivo." (PMID 34093543, 2021). "Therefore, our data suggest a tumor-supportive role of IL-33 during nutrient deprivation of regulatory CD8+ T lymphocytes in vitro." (PMID 34504486, 2021). "In addition, IL-33 induced the tumoricidal effect of eosinophils, directly killing tumor cells by increasing the effector molecules, such as markers of degranulation (CD63, CD107a), activation (CD69), and adhesion molecules, such as CD11b/CD18 and ICAM-1." (PMID 34209038, 2021). "Collectively, these results indicate that ILC2s from cancer patients are more prone to secrete cytokines, which may be related to their increased exposure to IL-33, both systemically and in the tumor microenvironment." (PMID 33953160, 2021). "Genetic ablation of IL-33 signaling in ApcMin/+ mice or inhibition by using neutralizing antibodies led to reduced proliferation, increased apoptosis and diminished angiogenesis in polyps, which overall reduced the tumor burden." (PMID 33435303, 2021). "Notably, it was also demonstrated that eosinophils can prevent tumor metastasis and growth of primary tumors in a IL33 dependent manner." (PMID 34283042, 2021). "Besides, CAFs promoted IL-33 expression in GC cells, and IL-33 overexpression reversed sh-NORAD-mediated tumor suppressive effects." (PMID 34895039, 2021). "Additionally, an elevated count of CD206+ M2 type macrophages, which infiltrated the ESCC tumours, was observed, and this increase had a positive correlation with the secretion of IL‐33." (PMID 33305406, 2021). "We found that IL‐33 resulted in an enhanced tumour volume compared with PBS." (PMID 33305406, 2021).
tumor (continued). "Consequently, the increase in IL‐33 and the decrease in OPN in peripheral blood and tumor tissues suggested IL‐33 and OPN as potential indicators for the efficacy of the early treatment of tumors with cetuximab." (PMID 34664425, 2021). "An increased percentage of IL-13-expressing intratumoral ILC2 was observed in parallel with the recruitment of immune-suppressive TAMs, IL-10-expressing DCs and MDSCs in an IL-33-treated breast cancer model with accelerated tumor progression and lung/liver metastases." (PMID 34884995, 2021). "Furthermore, macrophage-derived glycoprotein non-metastatic B facilitates the expansion of CSCs through CD44/IL-33 axis and promote metastasis in mouse tumor models." (PMID 35071018, 2021). "IL‐33 is also known to be closely related to tumor survival, growth, and angiogenesis." (PMID 34664425, 2021). "Being a negative regulator, sST2 could inhibit tumor growth and metastasis by suppressing IL-33-induced angiogenesis, Th1-, Th2-immune responses, as well as the infiltration and M2 polarization of macrophages." (PMID 34209038, 2021). "It is more likely that IL-33 released from these stromal cells could interact with the TME and enhance the anti-tumor immune responses, which may explain the better prognosis of the high IL-33 groups of the metastasis sub-cohorts." (PMID 33621202, 2021). "Indeed, IL-33 promoted the acidification of the tumor microenvironment, leading to the reduction of glucose." (PMID 34203391, 2021). "In addition, IL-33 can acts directly on tumor cells to enhance chemoresistance, highlighting that IL-33/ST2 targeting should be considered further for SCC therapies." (PMID 33634137, 2021). "An in vivo study confirmed the functional role of IL-33/CXCR4 in tumor initiation and metastasis." (PMID 34298657, 2021). "In addition, endogenous IL-33 production is also responsible for an effective anti-tumor response through CD8+ T cells." (PMID 34209038, 2021). "Targeting of IL‐33 or its cellular source may serve to be beneficial for empowering viral and tumor immunity, given the importance of this intriguing cytokine for promoting CD8+ T‐cell expansion." (PMID 33222176, 2021). "More significantly, our finding revealed that DPP-4i also triggered NF-кB-dependent NLRP3 inflammasome activation, leading to caspase-1-mediated processing of IL-1β and IL-33, two critical proinflammatory cytokines for the tumor-immune-suppressive microenvironment." (PMID 34631556, 2021). "Consequently, IL‐33‐induced macrophage MMP‐9 robustly mitigates the tumor killing‐effect by T cells." (PMID 34486239, 2021). "Importantly, endogenous IL-33/ST2 signaling boosted tissue-specific cancer immunity by activating tumor-infiltrating ILC2s to prime CD8+ T cells in mouse models of PDAC." (PMID 34209038, 2021). "Thus, we concluded that in ESCC, elevated expression of IL‐33 at the tumour site was correlated with the accumulation of macrophages and M2 macrophage differentiation." (PMID 33305406, 2021). "Tumor tissue shows increased endogenous IL-33 expression, contributing to cancer progression." (PMID 33806300, 2021). "Moreover, microscopic analysis of IL-33-expressing cells in the TME of artLCMV-TRP2-treated Cxcl13-Cre/tdTom EYFP mice revealed cytokine-positive EYFP+ cells at the tumor margin." (PMID 34354077, 2021). "On the other hand, in a mouse model for metastatic lung tumor, systemic administration of IL-33 induced the expansion of IL-5-producing ILC2s, which recruited and sustained eosinophils, critically contributing to increased tumor cell death, and thus preventing metastasis." (PMID 34209038, 2021). "Many studies have identified the key role of IL‐33 in tumor growth and the treatment of CRC." (PMID 34664425, 2021).
tumor (continued). "However, another study reported the opposite result, and the controversy about the functional role of IL-33 in tumor–stromal signaling, still exists." (PMID 34298657, 2021). "This HIF-dependent activation of CXCR4 that is mediated by IL-33 may suggest a novel mechanism for the induction of tumor progression." (PMID 34298657, 2021). "Like IL-18, IL-33 was shown to have pro- and anti-tumor effects." (PMID 33261061, 2020). "However, in the context of cancer, IL-33 aids in tumor immune evasion by upregulating the activity, survival and expansion of myeloid derived suppressor cells via ST2 signaling, which was reduced in ST2−/− mice." (PMID 32363166, 2020). "Notably, NK cell activity on melanoma tumor growth was improved, when IL-33-activated ILC2s were depleted, because they strongly upregulated CD73 ecto-enzyme which, in vivo, suppress T and NK cell functions by upregulating the suppressive adenosine in TME." (PMID 33233582, 2020). "Thus, the balance between tumor suppressing and tumor promoting activities of IL33 are highly context dependent, and most likely dictated by the mixture of cell types responding to IL33." (PMID 32719677, 2020). "It has been reported that IL‐33 can activate mast cells to produce a chemotactic cytokine, which promotes the accumulation of tumor‐associated macrophages (TAM) and supports the growth of tumor vascular network in gastric cancer." (PMID 32566227, 2020). "IL-33 can synergize with IL-3 to induce IL-9 production in human basophils, which may support tumor immunity." (PMID 33329534, 2020). "Furthermore, IL-33 has been reported to significantly modulate the tumor microenvironment by recruiting immune cells in lung carcinogenesis, both in vitro and in vivo." (PMID 33276627, 2020). "Collectively, these studies support our work on the role of IL-33 in reducing tumor growth in CRC." (PMID 32923137, 2020). "This may be because systemic injection of IL-33 elicits a broad immune response that promotes tumour growth in mice." (PMID 33308251, 2020). "Second, by mechanisms involving angiogenesis, IL‐33 promotes tumor proliferation." (PMID 32566227, 2020). "Studies utilizing antibodies IL33/ST2 in tumor models in mice." (PMID 32719677, 2020). "Although these dual effects may be explained by the localization of IL-33, it seems to be more complicated, since administration of recombinant IL-33 leads to both pro- and anti-tumor effects." (PMID 33261061, 2020). "Reduction in tumor growth is significantly enhanced when eosinophils are activated by IL-33." (PMID 32923137, 2020). "On the other hand, IL-33 may also limit tumor growth in other conditions, through the activation of cells involved in anti-tumor immunity by activating NK cells and CD8+ T cells." (PMID 32003751, 2020). "Blocked ST2 or knockdown IL-33 enhanced temozolomide induced anti-tumor effects." (PMID 32003751, 2020). "In addition, the tumour volume increased rapidly after IL-33 treatment, with significant difference at multiple time points compared with that in untreated mice." (PMID 33308251, 2020). "A tumor promoting role for IL33 was confirmed independently." (PMID 32719677, 2020). "To confirm this, we first measured sST2 and IL-33 in the sera of tumor-bearing mice." (PMID 32340025, 2020). "According to the different sources of IL-33 in LSCC and OCSCC, we propose a hypothesis that stroma-derived IL-33 could favor tumor progression, while epithelial-derived IL-33 could favor antitumor immune responses in HNSCC." (PMID 33634017, 2020). "Taken together, IL-33 may be a key tumour promoter of HCC proliferation and tumourigenicity, an important mediator, and a potential therapeutic target for regulating HCC progression." (PMID 33308251, 2020). "Likewise, IL33 signaling significantly shapes immune responses in the tumor microenvironment, but these effects remain often dichotomous when assessed in experimental models of cancer." (PMID 32719677, 2020).
tumor (continued). "Moreover, the mechanism of IL-33 was explained in terms of tumour microenvironment remodelling, secretion of factors promoting tumour proliferation, and microvascular density." (PMID 33308251, 2020). "IL-33 enhanced the mRNA levels of pro-inflammatory factor TNFα, which might stimulate tumour proliferation and angiogenesis." (PMID 33308251, 2020). "However, they formed tumors of equivalent size in IL-33 KO mice, indicating the involvement of IL-33 signaling in the difference in orthotopic tumor growth between Panc02-shCont and Panc02-sh#5 cells in wild-type mice." (PMID 32340025, 2020). "However, when IL-33 Eos were injected i.v. into ∆dblGATA-1 mice, tumor volumes and weights were significantly reduced." (PMID 32923137, 2020). "In this scenario, the IL-33-mediated activation of ILC2 cells might control the development of metastasis by promoting tumor immune-surveillance through eosinophil infiltration due to ILC2-derived IL-5 and IL-13." (PMID 33138017, 2020). "The results showed that IL-33 reduced the anti-tumor effect of TMZ." (PMID 32003751, 2020). "Recent reviews on the role of IL-33/ST2 (IL-33 receptor) in tumorigenesis have discussed in more detail how remodeling of the tumor microenvironment by IL-33 may either promote or reduce tumor growth." (PMID 32923137, 2020). "The tumour weight was significantly higher in the IL-33-treated than in the PBS-treated mice." (PMID 33308251, 2020). "In the current study, we, therefore, used two in vivo models to investigate whether eosinophils are involved in the effects of IL-33 on tumor growth in CRC." (PMID 32923137, 2020). "Tumor, epithelial and immune cells express sST2 at various levels, which may contribute to regulate the availability of IL-33 in the TME." (PMID 33329534, 2020). "In cancer, IL-33 is a possible tumor promotion substance by its direct effect on cancer cells to promote cell proliferation, growth, and metastasis, or an indirect effect for remodeling the tumor microenvironment to induce angiogenesis." (PMID 33046978, 2020). "Moreover, emerging evidence supporting a role for IL-33 in a number of cancers together with its potential to reprogram the tumor immune environment raises the obvious question on the impact of IL-33 in current and future cancer therapies." (PMID 33447733, 2020). "Several studies have supported the pro-tumour effect of IL-33, in line with our findings." (PMID 33308251, 2020). "Moreover, IL-33-overexpressing B16 melanoma cells have slower growth than WT cells, and the use of anti-PD-1 mAb improves this delay of tumor growth." (PMID 33261061, 2020). "Importantly, fibroblasts, endothelial and epithelial cells are also the major cellular sources of IL33 production in the tumor microenvironment." (PMID 32719677, 2020). "Here we found that the inhibitory effect of TMZ on tumor cell proliferation could be reduced by treating with IL-33." (PMID 32003751, 2020). "Thus, we identify TNF-α/IL-33/ST2L signaling as a mediator of the tumor–stromal cell interaction in GC." (PMID 31659258, 2020). "Importantly, and similar to the human xenografts, the mere expression of IL-33 resulted in enhanced tumor growth, increased infiltrating TAMs, and decreased the overall survival." (PMID 33020472, 2020). "Degranulation of eosinophils seems to be a major mechanism that contributes to the IL-33 dependent anti-tumorigenic effects while the change in the tumor microenvironment may play a minor role." (PMID 32923137, 2020). "In addition, more eosinophils infiltrated tumors in CT26 tumor-bearing ∆dblGATA-1 mice injected with IL-33 Eos vs. mice injected with IL-5 Eos." (PMID 32923137, 2020).
tumor (continued). "However, when mice were grafted with the metastatic tumor cells engineered to produce IL-33, the proportion of ILC2s was higher and the tumor growth and metastases were reduced." (PMID 33233582, 2020). "Moreover, IL-33-treated mice exhibited a pronounced increase in CD11c−CD11b+Gr1+ MDSCs, which led to tumour immune escape and tumourigenesis." (PMID 33308251, 2020). "A role for IL‐33 in the regulation of carcinogenesis and tumor growth and metastasis has emerged." (PMID 32566227, 2020). "Therefore, it seemed likely that the decrease in sST2 in the tumor microenvironment led to activation of IL-33/ST2L signaling, leading to either activation or suppression of other genes in stromal cells." (PMID 32340025, 2020). "Moreover, we observed a decrease in frequencies of intratumoural NK cells in tumour-bearing mice with IL-33 treatment." (PMID 33308251, 2020). "We found that systemic IL-33 administration significantly promoted the tumour size in vivo." (PMID 33308251, 2020). "Our data suggest that eosinophils are needed for IL-33-dependent reduction of tumor growth." (PMID 32923137, 2020). "IL-33 mediates the invasion of tumour-associated fibroblasts promoting the development of head and neck squamous carcinoma in the TME, suggesting that IL-33 may be a key mediator between the stromal cells and tumour." (PMID 33308251, 2020). "Anti-ST2 or knockdown IL-33 increased the sensitivity of tumor to temozolomide." (PMID 32003751, 2020). "We can report that IL-33 is a potent cytokine that diminishes tumor growth in both models." (PMID 32923137, 2020). "In OCSCC, IL-33 may play a role in orchestrating the immune responses against tumor cells and act as an antitumor factor." (PMID 33634017, 2020). "IL-33 also induced an increase in the number of tumor infiltrating eosinophils." (PMID 33329534, 2020). "However, IL-33 enhances type II immune response accelerating tumour progression in tumour-bearing animals." (PMID 33308251, 2020). "Further, IL-33 promotes inflammatory events in tumours and activates pro- or anti-tumour responses." (PMID 33308251, 2020). "In HNSCC, several studies have demonstrated that IL-33 may favor tumor progression by promoting tumor aggressiveness, angiogenesis or modulation of the tumor immune microenvironment (TIME)." (PMID 33634017, 2020). "Both IL-33 knockdown or anti-ST2 treatment enhanced the anti-tumor effect of TMZ." (PMID 32003751, 2020). "High concentrations of IL-33 could stimulate more tumor cells to pass through the chambers, and the results were statistically significant in both two cell lines." (PMID 32003751, 2020). "To date, the roles and mechanisms of IL-33 in tumours remain controversial." (PMID 33308251, 2020). "Targeting IL-33 removes NK cell suppression and reduces tumor burden." (PMID 33261061, 2020). "However, the role of IL-33 in cancer remains controversial, with pro-tumor and antitumor effects in different settings." (PMID 33634017, 2020). "Notably, co-culture of IL-33 EO with tumor cells in the presence of anti-CD18 blocking mAb significantly inhibited the formation of eosinophil-tumor cell conjugates and significantly reduced tumor cell killing." (PMID 31717819, 2019). "In animal tumor models, IL-33 has been described to increase MDSC growth." (PMID 31652497, 2019). "Interestingly, both activated YAP and myr-AKT are necessary for tumor formation, and omission of IL-33, a potent biliary mitogen, significantly reduces the efficiency of tumor formation from ~ 70% down to ~ 20%." (PMID 30815737, 2019). "Whether the IL‐33/ST2 axis on Treg cells plays a role in tumour progression has yet to be established." (PMID 31032905, 2019). "A different field for a novel employment of IL-33 could be the vaccine therapy of neoplasms, as IL-33 works as a promoter of memory T cell immunity." (PMID 31652497, 2019). "Furthermore, IL-33 inhibits tumor growth by contributing to the proliferation, activation and infiltration of CD8+ T cells and NK cells." (PMID 31396219, 2019).